SOD1 (superoxide dismutase 1)
Diseases named in the same sentence as SOD1 in open-access papers (continued):
Sharing a sentence is not in itself a finding about the gene and the disease.
diabetes (continued). "Diabetes disrupted the oxidation-antioxidation balance, while crocin improved the antioxidant state in the liver by significantly affecting SOD1 gene expression and/or by restoring SOD and total antioxidant capacity (TAC) levels." (PMID 32161725, 2020). "Nevertheless, in our experiment crocin did alter SOD1 gene expression and compensated for the significant increase induced by diabetes." (PMID 32161725, 2020). "It was also reported that it increases oxidative stress during diabetes and decrease SOD-1 expression." (PMID 32899471, 2020). "That is, a significant decrease in mRNA levels was inversely proportional with the upregulated protein levels, indicating a post-translational activation of SOD1 with diabetes." (PMID 30602713, 2018). "Diabetes significantly suppressed the expression levels of major antioxidant enzymes; cat, gpx, sod-1, and gstmu compared to control group (p < 0.05)." (PMID 30602713, 2018). "The change in the amount of SOD1 mRNA and protein levels with diabetes were contradictory to each other." (PMID 30602713, 2018). "Here, we verified that diabetes can slightly increase Nrf2 expression and function, which were reflected by HO-1 and SOD-1." (PMID 30622669, 2018). "After 8 weeks following diabetes induction, the expression of SOD1 was unchanged; however, the catalase expression was higher compared to CT." (PMID 28781721, 2017). "Diabetes mellitus can increase the activity of SOD and gene expression of SOD1 in gingival tissue of periodontitis patients." (PMID 29180965, 2017). "AGE/RAGE signaling has been implicated in oxidative stress associated with diabetes-mediated vascular calcification through activation of Nox-1, TGF-β mediated fibrosis, NFκB, and ERK1/2 pathways and decreased expression of SOD-1." (PMID 27547766, 2016). "AGE/RAGE signaling has been shown to increase oxidative stress to promote diabetes-mediated vascular calcification through activation of Nox-1 and decreased expression of SOD-1." (PMID 27547766, 2016). "Only then, we can consider any potential benefits of SOD1 overexpression in chronic intermittent hypoxia-, diabetes-, and aging-induced impairment of baroreflex arc as shown in our previous studies." (PMID 26823951, 2016). "Although diabetes considerably decreased the activity of serum SOD as recorded in the present study, which agreed with the work on food regimens supplemented with prebiotics, probiotics and synbiotics that up-regulate SOD-1." (PMID 27164129, 2016). "It was observed that, diabetes decreased the activities of both SOD-1 and GST-Mu below the control values." (PMID 25905778, 2015). "SOD1 dysfunction which results in an increased intra-cellular reactive oxygen species also plays a major role in diabetes neuropathy." (PMID 24661645, 2014). "Accordingly, diabetes-decreased renal mRNA expression of superoxide dismutase 1 (SOD1), catalase, and glutathione peroxidase (GPx) was restored after MG132 intervention." (PMID 22645602, 2012). "Cat, Sod1, Sod2, Prkca, and Nos1 expression levels were decreased, while Ncf1, Xdh, and Cyba expression levels were increased in diabetes." (PMID 20979611, 2010). "With respect to diabetes, SOD1 KO accelerates the development of diabetic nephropathy and cataract formation." (PMID 20979611, 2010). "Among the 53 over-represented ROS-diabetes targets, SOD1 was the most over-represented and was differentially expressed under diabetic and non-diabetic conditions." (PMID 20979611, 2010). "The most common pathological conditions in contemporary culture, such as inflammatory bowel disease, obesity and its consequences—diabetes and hypertension—and chronic obstructive pulmonary disease, have been linked to changes in SOD (SOD1 and SOD3) activity and its expression." (PMID 40867576, 2025).
diabetes (continued). "Interestingly, a recent study showed compromised osseointegration of titanium implants in the maxilla of rats with diabetes, with increased oxidative stress markers, such as p47 and Nox2, and decreased SOD1 in the bone adjacent to the implant in the DM group." (PMID 37760090, 2023). "On the cellular level, we demonstrated a dose-dependent downregulation of cytokines, chemokines and NOX isoforms by hidrosmin in VSMC exposed to hyperglycemia, as well as SOD1 and catalase upregulation, thus confirming its anti-inflammatory and antioxidant action in the diabetes context." (PMID 36552707, 2022). "Diabetes induced downregulation of both SOD-1 and SOD-2 protein." (PMID 33923282, 2021). "Furthermore, we had also detected the oxidative stress level (upstream of ASK1-JNK1/2 signaling) and found that diabetes significantly inhibits SOD1 and SOD2 expressions and elevates NOX2 level in the hippocampus." (PMID 32766246, 2020). "Sod1 and P4hb showed significant differences in mRNA expression between the livers of gerbils with diabetes and control animals, implying that these genes play an important role in the mechanism of diabetes in gerbils." (PMID 29394254, 2018). "In our study, Sod1 expression was lower in gerbils with diabetes." (PMID 29394254, 2018). "SOD1 overexpression abrogated diabetes-induced PKCα activation and superoxide production." (PMID 28474670, 2017). "Furthermore, diabetes also significantly downregulated the mRNA expression of Nrf2 and its downstream antioxidant genes SOD-1 and HO-1 in the aorta of T2DM compared to control." (PMID 24707343, 2014). "As the down-regulation of CCS in diabetes could well impair its ability to deliver copper to SOD1, we investigated whether SOD1 activity was altered in diabetes." (PMID 24927960, 2014). "Since Nox4 is the major source of ROS in the kidneys during the early stages of diabetes, interventions to reduce ROS production by targeting Nox4 or increasing SOD1 may be an attractive therapeutic strategy." (PMID 23991195, 2013). "SOD1 was the most over-represented in the ROS-diabetes targets." (PMID 20979611, 2010). "Association of the SOD1, SOD2 and CAT polymorphism, BMI, age, duration of diabetes, sex, type of diabetes and SOD activity as independent variables with the presence of microangiopathy or macroangiopathy as dependent variables was performed using a logistic regression model." (PMID 18423055, 2008). "The possibility of protein-level reductions in other antioxidant enzymes, such as SOD1, SOD2, and catalase, under diabetes distress remains to be explored and constitutes a major limitation of our study." (PMID 41462586, 2025). "Research also found that tea polyphenols lowered ROS in diabetic oocytes while boosting the expression of Sod1, Sod2 and other antioxidant genes, thereby mitigating the detrimental impact of STZ-induced diabetes on oocyte quality." (PMID 40110863, 2025). "Through the activation of Nox-1 and the decreased expression of SOD-1, AGE/RAGE signaling has been demonstrated to increase oxidative stress and promote diabetes-related vascular calcification." (PMID 35458596, 2022). "Through the activation of Nox-1 and the reduced expression of Superoxide Dismutase-1 (SOD-1), AGE-RAGE signaling has been demonstrated to enhance oxidative stress and accelerate diabetes-related vascular calcification." (PMID 35956419, 2022). "Crocin treatment contributed in restoring some parameters after diabetes induction, primarily by affecting significantly hepatic transaminases ALT and AST, SOD1 and PAI-1 gene expression and nephric H2O2 decomposing activity." (PMID 32161725, 2020). "Increase in oxidative stress in response to diabetes was measured as an increase in the expression of RAGE and SOD-1, and formation of ROS and H2O2." (PMID 28678840, 2017).
diabetes (continued). "Quantitative real time PCR results demonstrated that gene expression levels of main antioxidant enzymes SOD-1, SOD-2 and detoxification enzymes GST-Mu and GST-Pi were suppressed with diabetes." (PMID 25905778, 2015). "In this study, docking of alginate, a biologically active polysaccharide, was performed to gain a theoretical understanding of its possible interactions with key therapeutic enzymes (COX-1, α-amylase, BChE, SOD1, and GPX4) related to inflammation, diabetes, neurodegeneration, and oxidative stress." (PMID 41304964, 2025). "Another interesting finding of the present study was the lack of association between SOD-1 and LOX-1, as markers of oxidative stress, and diabetes." (PMID 39859119, 2025). "Yet, it was also found, in non-alcoholic fatty liver disease (NAFLD) with and without diabetes mellitus, SOD-1 activity was decreased." (PMID 39330521, 2024). "The SOD isozymes (SOD1,SOD2, SOD3) are often liked with the incidence of obesity and diabetes." (PMID 37808375, 2023). "Antioxidant enzymes SOD1/SODC and SOD2/SODM were also increased by diabetes in wild‐type mice." (PMID 34277994, 2021). "As far as SOD1 gene expression in the liver is concerned, there is no consistent effect of the induction of diabetes and/or of the administration of antioxidants." (PMID 32161725, 2020). "Our laboratory has applied knockouts of GPX1 (Gpx1-/-), SOD1 (Sod1-/-), and both (dKO) mice and GPX1-overexpressing (Gpx1-OE) mice to study the metabolic roles and molecular mechanisms of these redox enzymes in the development of insulin resistance and diabetes." (PMID 37107224, 2023). "However, the current study did not analyse the expression of SOD1 in the rat liver at the early onset of diabetes." (PMID 36818894, 2022). "Saxagliptin, in combination with metformin, can help improve endothelial dysfunction in early diabetes before macrovascular complications appear, and this effect was potentially related to upregulation in CD34+ endothelial progenitor cells for antioxidant SOD1." (PMID 34531738, 2021). "Further study confirmed that the blockade and/or activation as well as deficiency of KCa3.1 could not affect the expression of NOX2 and SOD1, suggesting that mitochondria might be a dominant system by which KCa3.1 regulates ROS generation in diabetes." (PMID 33777959, 2021). "The reduction in SOD2 may underline the finding that mitochondria are the main site of producing superoxide in diabetes, Since SOD2 plays a central role in metabolizing O2.− in mitochondria the maintained level of SOD1 may prevent O2.− overproduction in diabetic conditions." (PMID 29870994, 2018). "In addition to TXNIP and the Trx/TrxR redox system, other ROS generating systems (NADPH oxidase and Xanthene oxidase) and anti-oxidants (GSH, SOD1, and SOD2) may also be involved in dysregulation of the mitochondrial–lysosomal axis in diabetes and under glucolipotoxicity." (PMID 34940029, 2021). "Additionally, CAT and SOD1 genes/proteins are assumed to highly influence the control of the PPI network because these are also known as antioxidative enzymes having a very potent role in diabetes and diabetes-related complications including diabetic nephropathy." (PMID 34367469, 2021). "In contrast, Sod1 exhibits an unusual pattern, in that it is not influenced by diabetes but was induced by the ketogenic diet in both wild-type and db/db mice, suggesting that the induction of Sod1 could mediate part of the protective effect of the ketogenic diet." (PMID 21533091, 2011). "Moreover, western blot further confirmed total superoxide dismutase 1 (SOD1), heme oxygenase-1 (Hmox1) and glutamate cysteine ligase (GCLc) expression at protein level, supporting the hypothesis of PNS up-regulated antioxidants to ameliorate diabetes-induced oxidative stress." (PMID 37337262, 2023). "No variations of SOD1 and SOD2 levels were found but diabetes led to a rise of SOD2 acetylation in DIAB and DIAB+GTE groups (+44% and +35%, respectively, p < 0.001)." (PMID 31690052, 2019).
diabetes (continued). "The levels of SOD1, SOD2, and SOD3 in the three groups with diabetes were not significantly changed." (PMID 27830142, 2016). "The presented findings show that the genotype distribution of the SOD1 and SOD2 in patients with diabetes mellitus can differed from nondiabetic individuals." (PMID 18423055, 2008). "Diabetes-induced reduction of CAT and increase of SOD1 protein levels in rat kidney tissue were normalized by resveratrol toward the control values, whereas down-regulated mRNA levels of CAT, GPx and SOD1 were not affected by resveratrol treatment." (PMID 33803588, 2021).
colitis (178 papers, 2009 to 2026). Inflammation of the colon. "Given the study showing the reduced enzymatic activity of GPX and GSH in SOD1 deficiency in a DSS-induced colitis model, we cannot exclude the possibility that a lower expression of GPX1 in our study is the result of reduced SOD in colitis." (PMID 38668322, 2024). "Our finding is further supported by the evidence that SOD1 deficiency exacerbates DSS-induced colitis and SOD treatment significantly attenuates colonic inflammation in experimental colitis." (PMID 38668322, 2024). "Interestingly, a recent work has shown that SOD1 knockout mice exhibited increased susceptibility for DSS-induced colitis with upregulation of ROS and p38-MAPK signaling, in which oral administration of SOD could ameliorate the disease phenotype." (PMID 34208517, 2021). "SOD1 inhibits DSS-induced colitis through a dual mechanism of antioxidant activity and immunomodulation." (PMID 40722913, 2025). "In 2020, Hwang and colleagues investigated the role of Cu/Zn-SOD (SOD1) in oxidative stress during colitis using a dextran sulfate sodium (DSS)-induced SOD-knockout (KO) mouse model of acute colitis." (PMID 40430897, 2025). "The influence of SOD1 on colitis has been attributed to its capacity to suppress oxidative stress, immune response, and cell death." (PMID 38467701, 2024). "Previous studies have shown that SOD1 overexpression not only protects cancer cells from oxidative stress but also suppresses pro-inflammatory immune responses in colitis by preventing oxidative stress." (PMID 37822927, 2023). "SOD1, an enzyme that plays an important role in protecting tissue against oxidative stress, is indispensable in suppressing the development of colitis." (PMID 38004239, 2023). "HBPF diet also increased the gene expression of Pparg and enzymatic antioxidants (Sod1, Sod3 and Gpx1), genes all reported to be involved in promoting an immunosuppressive Treg cell response and to protect against colitis." (PMID 23776564, 2013). "It is possible that SOD1 may already be maximally expressed in response to induced colitis, leaving little room for further potentiation by BC." (PMID 40002416, 2025). "Dextran sodium sulfate-induced SOD1 knockout colitis mice increased the levels of neutrophils, monocytes, pro-inflammatory CD11c+ macrophages, and CD11b+CD103− dendritic cells and decreased the levels of anti-inflammatory CD206+ macrophages and CD11b−CD103+ dendritic cells." (PMID 37759978, 2023). "In addition, the SOD1 enzyme prevented the occurrence of colitis and affected the stability of cecal flora in mice." (PMID 37759978, 2023). "A published study suggested that injection of a SOD1 enzyme produced by Bacillus amyloliquefaciens into dextransulfatesodium (DSS)-treated SOD1 knockout mice could prevent colitis by inhibiting p38 mitogen-activated protein kinase (MAPK)/NF-κB signaling." (PMID 37759978, 2023). "The decrease in the expression of the biological antioxidant superoxide dismutase 1 (SOD1) exacerbated DSS-induced colitis in mice through increased ROS-induced oxidative stress and pro-inflammatory immune responses; conversely, an increase in SOD1 expression protected against DSS-induced colitis." (PMID 35631174, 2022). "Furthermore, the SOD3-mediated, anti-inflammatory role in skin inflammation by inhibiting the expression of proinflammatory cytokines, including TNF-α, IL-1β, IL-6, and IL-8, and SOD1-mediated suppression of proinflammatory immune responses against oxidative stress in colitis, were also reported." (PMID 40825682, 2025). "However, the role of SOD1 in oxidative stress in colitis is unclear." (PMID 36590401, 2022). "Moreover, the upregulation of anti-oxidative genes, including ferritin heavy chain 1, heme oxygenase 1, NAD(P)H quinone oxidoreductase 1, and superoxide dismutase 1, in the colons of colitis/SPH group was observed compared with the control peptide treatment group." (PMID 36139127, 2022).
colitis (continued). "Nevertheless, the connection between HSPA9 and the regulation of oxidative stress through SOD1 enhances our understanding of the role of HSPA9 in regulating mitochondrial ROS and colitis symptoms." (PMID 38467701, 2024). "Consequently, a low expression of SOD1 may contribute to the severity and progression of colitis." (PMID 38467701, 2024). "SIRT5 desuccinylates and activates SOD1 to eliminate ROS, desuccinylates and activates PKM2 to block macrophage IL-1β production and prevent DSS-induced colitis, and desuccinylates and activates SHMT2 to drive cancer cell proliferation." (PMID 34930316, 2021). "Strong correlation of HIF-1α mRNA level to GPx1, SOD1, and IL-6 mRNA expression suggests involvement of HIF-1α in transcriptional regulation of these genes during colonic inflammation and HBO2." (PMID 27656047, 2016). "To summarize, colitis resulted in GPx1 gene upregulation and CAT gene downregulation, while HBO2 downregulated SOD1 and further upregulated GPx1 in a tissue-specific manner." (PMID 27656047, 2016). "Thus, we assessed the main antioxidant enzymes (SOD1, SOD2, CAT, GPx) in a TNBS-induced colitis model in animals previously treated with BC." (PMID 40002416, 2025). "Our study showed that both SOD1 and SOD2 are downregulated in experimental colitis." (PMID 38668322, 2024). "In addition, it has been found that probiotics such as Lactobacillus plantarum ZDY2013 and Bifidobacterium bifidum WBIN03 can regulate the secretion of antioxidant enzymes, SOD1, GPX2 and CAT, by activating the Nrf2 pathway, while achieving the effect of alleviating colitis." (PMID 35681318, 2022). "The mucosal expression of mRNA for TNF-α, IL-1β, iNOS, COX-2, SOD-1, SOD-2, GPx mRNAs, and the hypoxia inducible factor (HIF)-1α protein expression were upregulated in colonic mucosa of treadmill exercising HFD mice with colitis compared with those without exercise." (PMID 31117199, 2019).